ID4 (inhibitor of DNA binding 4)
Diseases named in the same sentence as ID4 in open-access papers (continued):
Sharing a sentence is not in itself a finding about the gene and the disease.
breast cancer (continued). "Among the 340 under-expressed genes containing the 586 hyper-methylated CpGs, there were several tumor suppressor genes with under-expression that has previously been observed in breast cancer, such as L3MBTL4, ID4, RUNX3, PROX1, SFRP1 and others." (PMID 27386846, 2016). "Four marker genes (ID4, SOSTDC1, SLC26A2, TNC) relevant to drug activity to cisplatin on breast cancer cells were derived from the signature genes for breast cancers." (PMID 26824188, 2016). "It has been reported that miR-335 suppresses breast cancer metastasis by targeting SOX4 and Tenascin C, small cell lung cancer metastasis by targeting IGF1R and RANKL, and induces apoptosis of breast cancer cells by regulating ERα, IGF1R, SP1, and ID4." (PMID 26098312, 2015). "Overexpression of miR-342 in these cells reduced ID4 and increased BRCA1 expression, supporting a possible role of this mechanism in breast cancer." (PMID 24475217, 2014). "We functionally demonstrated the interactions between miR-342, ID4 and BRCA1 in a model provided by ER-negative MDA-MB-231 breast cancer cell line that presented high levels of ID4." (PMID 24475217, 2014). "The increase of ID4 expression after promoter demethylation was 119-fold in T47D cells, 38-fold in MCF7 cells and 19-fold in BT20 breast cancer cells." (PMID 18513385, 2008). "Thus, ID4 methylation status could serve as a prognostic biomarker in human breast cancer." (PMID 18513385, 2008). "Therefore, we analyzed ID4 expression and the activation of three YAP/TAZ signatures of the TCGA cohort in different subtypes of breast cancer." (PMID 38321003, 2024). "ID4 has been shown to promote chemo-resistance and stemness of glioma cells by promoting SOX2 expression, but has yet to be studied in the context of breast cancer resistance." (PMID 36291790, 2022). "ID4 ChIP-exo was conducted in biological duplicate in HCC70 and HCC1954 breast cancer cell lines." (PMID 32527287, 2020). "ID4 (inhibitor of differentiation) protein is highly expressed in TNBC cells and down-regulates BRCA1 pathways and exhibits anchorage-independent growth of breast cancer cells." (PMID 29298879, 2018). "The positive function of Id4 in tumor aggressiveness is best understood in breast cancer, but very little evidence is available regarding the role of Id4 protein in HCC." (PMID 28143562, 2017). "In this study we demonstrated in vitro that a mechanism involving the microRNA miR-342 and the two genes ID4 and BRCA1, which are frequently altered in breast cancer, could have a role in the pathogenesis of this tumor type." (PMID 24475217, 2014). "In addition, integrating pathway and gene information, we identified five (ID4, ANXA4, CXCL9, MYLK, FBXL7) and six (SQLE, E2F1, PTTG1, TSTA3, BUB1B, MAD2L1) known cancer genes significant for ovarian and breast cancer respectively." (PMID 22759382, 2012). "The expression of ID4 and BRCA1/ER inversely correlated in sporadic breast cancers." (PMID 21293053, 2010). "The expression level of ID4 and its regulatory mechanism play a crucial role in the study of breast cancer, but its oncogenic or oncostatic role has not yet been unanimously identified, and its regulatory mechanism in breast cancer still needs to be further elucidated." (PMID 40186425, 2025).
breast cancer (continued). "However, the expression of ID4 is negative in breast cancer, NSCLC, and its subtype datasets, but it is only positive in the SCLC dataset, which suggests a difference in expression levels according to the type of lung cancer." (PMID 36101460, 2022). "Result showed that ID4 may target the CBF1 pathway by directly binding to its promoter region via combination with MyoD1, therefore CBF1 activated the function of MRP1 to enhance the chemotherapy resistance in breast cancers." (PMID 32328189, 2020). "Moreover, the culture of human fibroblasts, another cell type usually present in the tumor stroma, with CM from breast cancer cells did not lead to ID4 induction, indicating that the observed effect is specific to the monocyte/macrophage lineage." (PMID 32054109, 2020). "Thus, the role of ID4 in breast cancer is not clear where both an oncogenic and a tumor suppressor function have been attributed." (PMID 32328189, 2020). "However, the role of ID4 in breast cancer is not clear where both an oncogenic and a tumor suppressor function have been attributed." (PMID 30139383, 2018). "Moreover, in breast cancer cells, Id4 and the tumor suppressor BRCA1 exist in a negative feedback loop." (PMID 23342267, 2012). "In breast cancer cells, Id4 and BRCA1 are in a negative feedback loop." (PMID 19500415, 2009). "Thus, ID4 may have the opposite function of ID1 and ID2, which are thought to have oncogenic properties in human breast cancer cells." (PMID 18513385, 2008). "Accordingly, 31.1% of the breast cancer specimens (53/170) exhibited no ID4 promoter methylation." (PMID 18513385, 2008). "However, our findings are not in accordance with the determined ID4 mRNA upregulation described for rat breast carcinoma cells." (PMID 18513385, 2008). "However, the role of ID4 in breast cancer cell motility has not yet been explored." (PMID 38321003, 2024). "Breast cancer patients harbouring a methylated ID4 promoter were found to have a decreased mean RFS time in comparison to patients without ID4 methylation in the tumour, supporting the hypothesis that a functional ID4 gene indeed confers tumour suppressive functions to human breast tissue." (PMID 18513385, 2008). "Unlike ID4, other members of the ID protein family (e.g., ID1 and ID3) are highly expressed in metastatic human breast cancers and exhibit pro-metastatic activity." (PMID 38188675, 2023). "In this study, we firstly confirmed that ID4 was highly expressed in the TNBC and Her-2 overexpression breast cancers, and its expression was negative correlated with ER and PR, which was consistent with Best and Garraway's reports." (PMID 32328189, 2020). "In our work, we found the Notch1 pathway was positively associated with ID4 expression both in MDA-MB-231 and MCF-7/Adr cells, and ID4 could activate CBF1 by directly binding to the CBF1 promoter region via combined with MyoD1, which was reported to be a negative transcriptor in breast cancer." (PMID 32328189, 2020).
prostate carcinoma (30 papers, 2009 to 2024). A carcinoma that arises from epithelial cells of the prostate gland. "Loss of ID4 expression is also frequently observed in prostate cancer suggesting its essential role as a tumor suppressor." (PMID 25115397, 2014). "Decreased Id4 expression with increasing grade of prostate cancer is also associated with Id4 promoter hyper-methylation." (PMID 24330748, 2013). "Many of the genes associated with prostate cancer and their respective knockout/transgenic phenotypes are also recapitulated in the Id4-/- model that support the role of Id4 in prostate cancer." (PMID 23786676, 2013). "In prostate cancer samples, loss of Id4 expression was also associated with promoter hypermethylation." (PMID 23342267, 2012). "At the mechanistic level, the transcriptional inactivation of Id4 is associated with aberrant promoter methylation in prostate cancer cell lines and tissue samples as demonstrated in this study and confirmed by others." (PMID 23342267, 2012). "A recent report suggested a positive association between Id4 expression and prostate cancer metastasis." (PMID 19500415, 2009). "At the mechanistic level, the transcriptional inactivation of Id4 is associated with aberrant promoter methylation in a model prostate cancer cell line DU145." (PMID 19500415, 2009). "Methylation specific polymerase chain reaction (MSP) analysis was performed to understand molecular mechanisms associated with Id4 expression in prostate cancer cell lines." (PMID 19500415, 2009). "ID4 is potential tumor suppressor and epigenetic inactivation of this gene linked with progression of prostate cancer, but loss gene this might be liable for advancement of pituitary prolactinoma." (PMID 33709028, 2021). "Id4 overexpression is able to arrest cell cycle and inhibit cell proliferation, which is associated with the increased expression of cyclin-dependent kinase inhibitors p21 and p27 in the prostate cancer cell line DU145 cells." (PMID 33936204, 2021). "ID4 promoter methylation was also correlated with the risk of prostate cancer." (PMID 31956659, 2019). "Our results demonstrate loss of Id4 expression in prostate cancer due to promoter hypermethylation." (PMID 23342267, 2012). "The HLH transcriptional regulator ID4 is a relatively new player in the prostate development and prostate cancer landscape." (PMID 33884281, 2021). "Experimental and meta-analysis has consistently directed towards the putative role of ID4 as tumor suppressor in prostate cancer and more importantly as a key regulator of mammalian prostate development as reported in this and our earlier studies." (PMID 33884281, 2021). "It is also regarded as a tumor suppressor gene because the methylation of ID4 promoter gene leading to ID4 silencing can also promote the development of colon cancer, gastric cancer, prostate cancer and hematological malignancies 31-34." (PMID 32328189, 2020). "On the other hand, some studies declared that the reduction of ID4 gene expression is responsible for prostate cancer development." (PMID 30876429, 2019). "In prostate cancer, Id4 acts as a tumor suppressor that increases cell apoptosis and inhibits cell proliferation through arresting S-phase progression." (PMID 31847356, 2019).
prostate carcinoma (continued). "Previous studies demonstrated that ID4 is highly expressed in normal ductal epithelial cells of the prostate, whereas ID4 expression is progressively lost with increasing stage of the prostate cancer due to promoter hypermethylation." (PMID 28252832, 2017). "Collectively, these results indicated that knockdown of ID4 enhances tumorigenicity of prostate cancer cells in the CRPC conditions, more importantly through FKBP52‐mediated AR signaling." (PMID 28252832, 2017). "Together, these results indicated that with subsequent loss of ID4, Hsp27 and FKBP52 promote nuclear translocation and transcriptional activity of AR, followed by increased cell proliferation in prostate cancer L(−)ID4 cell lines." (PMID 28252832, 2017). "A nanoparticle-based approach has been recently used to deliver recombinant Id4 protein as a biotherapeutic agent into prostate cancer cells or into prostate cancers in mice." (PMID 28122577, 2017). "ID4, a helix loop helix transcriptional regulator has emerged as a tumor suppressor in prostate cancer." (PMID 27487149, 2016). "Epigenetic silencing of ID4 promotes prostate cancer whereas ectopic expression in prostate cancer cell lines blocks cancer phenotype." (PMID 27487149, 2016). "ID4 promoter was also methylated in prostate cancer but un-methylated in adjacent normal in TCGA datasets that is supported by methylation specific PCR in tissue samples." (PMID 25115397, 2014). "Here, we report, to our knowledge for the first time, that ID4 is a PcG (Polycomb group) protein EZH2 target gene in prostate cancer." (PMID 25115397, 2014). "Knockdown of ID4 in LNCaP prostate cancer lines results in aggressive growth, increased cell survival and acquisition of castration resistance phenotype usually associated with advanced disease." (PMID 25115397, 2014). "Together, results from prostate cancer cell lines and prostate tissue suggested that ID4 is regulated in part by histone modifications in an EZH2 dependent manner." (PMID 25115397, 2014). "Collectively, our data indicate a PRC2 dependent mechanism in ID4 promoter silencing in prostate cancer through recruitment of EZH2 and a corresponding increase in H3K27Me3." (PMID 25115397, 2014). "We and others have shown that Id4 and Id1 expression is mutually exclusive in the normal prostate and prostate cancer." (PMID 23786676, 2013). "The prostate cancer cell line DU145 also lacks Id4 expression due to promoter hypermethylation whereas LNCaP cells express Id4." (PMID 24330748, 2013). "The molecular changes in the prostate observed in the Id4-/- mouse model were further confirmed in vitro using Id4 gene silencing and gain-of-function approaches in the prostate cancer cell lines LNCaP and DU145." (PMID 23786676, 2013). "Inhibitor of differentiation 4 (Id4), a member of the helix-loop-helix family of transcriptional regulators has emerged as a tumor suppressor in prostate cancer." (PMID 23786676, 2013).
prostate carcinoma (continued). "We and others have recently shown that Id4 is highly expressed in the normal prostate and decreased in prostate cancer due to promoter hypermethylation." (PMID 23786676, 2013). "Id4 was either over-expressed or silenced in prostate cancer cell lines DU145 and LNCaP respectively followed by analysis of PTEN, NKX3.1 and Sox9 expression." (PMID 23786676, 2013). "We used the Id4 -/- mouse model to evaluate further the role of Id4 in prostate development and its significance in prostate cancer." (PMID 23786676, 2013). "Second, Id4 protein expression is significantly decreased and in most cases undetectable in advanced stages of prostate cancer as detected by a highly specific rabbit monoclonal antibody." (PMID 23342267, 2012). "In the present study, we extend these observations and demonstrate that Id4 is down-regulated in prostate cancer due to promoter hypermethylation." (PMID 23342267, 2012). "A strong correlation between Id4 expression and its promoter hypermethylation in prostate cancer cell lines was observed." (PMID 23342267, 2012). "Our previous studies also suggested that Id4 is regulated by androgens in normal prostate epithelial cells and in androgen-sensitive prostate cancer cell line LNCaP." (PMID 23342267, 2012). "On the contrary, we provide multiple lines of evidence that demonstrate decreased Id4 expression in prostate cancer." (PMID 23342267, 2012). "We therefore re-evaluated Id4 expression in prostate cancer tissue using a highly specific anti-human Id4 rabbit monoclonal antibody BCH-9/82-12-50." (PMID 23342267, 2012). "This study strengthens our previous report which provided direct evidence that Id4 acts as a tumor suppressor in prostate cancer." (PMID 23342267, 2012). "Non-parametric Kruskal–Wallis analysis followed by post hoc Dunn' multiple comparisons test was used to determine statistical differences between Id4 staining intensity in normal prostate and prostate cancer tissue microarray specimens." (PMID 23342267, 2012). "Methylation specific PCR on bisulfite treated DNA was used to determine methylation status of Id4 promoter in laser capture micro-dissected normal, stroma and prostate cancer regions." (PMID 23342267, 2012). "On the contrary, our previous results demonstrated that Id4 acts as a potential tumor suppressor in prostate cancer." (PMID 23342267, 2012). "First, in LNCaP cell line-based prostate cancer progression model Id4 transcript is decreased from androgen-dependent LNCaP cells to androgen-independent LNCaP-C81 cells, with an intermediate expression observed in LNCaP-C-33 cells." (PMID 23342267, 2012). "In prostate cancer, a stage-dependent decrease in Id4 expression was observed with majority of high grade cancers showing no Id4 expression." (PMID 23342267, 2012). "In this study, we expand our observations of Id4 expression in established prostate cancer cell lines and prostate cancer tissue to demonstrate that Id4 expression is decreased in prostate cancer due to promoter hypermethylation." (PMID 23342267, 2012). "Our results demonstrate that Id4 expression is decreased in prostate cancer due to promoter hypermethylation." (PMID 23342267, 2012). "These analyses confirmed that Id4 promoter hypermethylation in prostate cancer results in decreased Id4 expression." (PMID 23342267, 2012). "Our results are therefore consistent with the epigenetic silencing of Id4 due to promoter hypermethylation in cancers: T-/natural killer acute lymphoblastic leukemia, gastric, breast colorectal, and prostate cancer." (PMID 23342267, 2012). "Id4 expression is low in PC3 prostate cancer cells but undetectable or weakly expressed in androgen-independent DU145 prostate cancer cells due to promoter hypermethylation." (PMID 23342267, 2012). "Laser capture micro-dissection (LCMD) was used to examine Id4 methylation in 41 prostate cancer samples, 19 benign and adjacent normal regions and 4 benign stroma adjacent to prostate cancer regions." (PMID 23342267, 2012).